KIF4A (kinesin family member 4A)
Diseases named in the same sentence as KIF4A in open-access papers (continued):
Sharing a sentence is not in itself a finding about the gene and the disease.
liver cancer (8 papers, 2017 to 2025). An epithelial or non-epithelial malignant neoplasm that arises from the liver. "High levels of KIF4A are associated with poor prognosis in liver cancer while KIF4A silencing suppressed the proliferation and migration of liver cancer cells, suggesting that KIF4A contributes to the malignant progression of liver cancer." (PMID 31072351, 2019). "Many studies have shown that the expression of KIF4A in liver cancer, cervical cancer and oral cancer tissues is up-regulated, and is positively correlated with poor prognosis." (PMID 34055488, 2021). "Results showed that KIF4A protein levels (18/18,100%) were increased in primary liver cancer tissues compared with adjacent normal liver tissues." (PMID 29396392, 2018). "We compared the gene expression profile of patients with high KIF4A expression and those with low KIF4A expressing in TCGA liver cancer cohort (total 371 patients, divided by the median KIF4A mRNA expression value)." (PMID 28646197, 2017). "One study reported that, in liver cancer, upregulation of KIF4A promotes cell proliferation by activating AKT signaling pathway, which makes liver cancer patients have a worse prognosis." (PMID 34097054, 2021). "KIF4A is also highly expressed in hepatitis B virus (HBV)-related liver cancer, and HBV stimulates KIF4A expression in HCC." (PMID 31072351, 2019).
bladder cancer (7 papers, 2021 to 2025). "In bladder cancer, KIF4A potentiated an immunosuppressive microenvironment by increasing the recruitment of myeloid-derived suppressor cells." (PMID 37752167, 2023). "We found that KIF4A mRNA expression was remarkably upregulated in bladder cancer tissue compared with that in normal bladder tissue." (PMID 37039264, 2023). "KIF4A dysregulation occurs in various tumors, including lung, liver, breast, and bladder cancer." (PMID 37039264, 2023). "Levels of CDCA3, CENPF, CENPA and KIF4A are correlated in bladder cancer." (PMID 34905505, 2021). "To explore the involvement of KIF4A in UBC, we compared KIF4A mRNA expression between bladder cancer tissue and normal bladder tissue from the GEPIA." (PMID 37039264, 2023). "Considering the regulatory role of YAP1/TEAD4 in KIF4A transcription in esophageal squamous cell carcinoma and the role of TEAD1 in chemoresistance of bladder cancer, we sought to investigate whether YAP1/TEAD1 is involved in KIF4A dysregulation in UBC." (PMID 37039264, 2023).
cervical carcinoma (7 papers, 2020 to 2025). A carcinoma arising from either the exocervical squamous epithelium or the endocervical glandular epithelium. "KIF4A is dominantly localized in the nuclear matrix and is associated with chromosomes during mitosis and mediates cytokinesis during cervical cancer progression." (PMID 41516135, 2025). "Recent studies show that KIF4A-low cervical cancers exhibit greater CNV burden and enrichment of NOTCH1 mutations—features associated with increased neoantigen load and immunotherapy sensitivity." (PMID 41361459, 2025). "Conversely, lower expression of KIF4A or specific mutations may suggest that patients could benefit from certain treatments; for instance, cervical cancer patients with reduced KIF4A expression demonstrated better responses to immunotherapy." (PMID 41361459, 2025). "KIF4A is recognized as a key player in the progression of cervical cancer, possibly promoting disease advancement by modulating the cell cycle." (PMID 41361459, 2025). "Special Finding: In the context of cervical cancer, KIF4A displays a distinct role that contrasts with its typically oncogenic function in other cancers, highlighting its context-dependent behaviour." (PMID 41361459, 2025). "Interestingly, KIF4A’s role can shift in certain contexts, such as cervical cancer, highlighting the need for the development of biomarker-based strategies to tailor precision medicine approaches." (PMID 41361459, 2025). "While KIF4A is typically detrimental in most cancers, it may play a protective role in specific contexts, such as cervical cancer, necessitating careful consideration of cancer types and molecular backgrounds when developing targeting strategies." (PMID 41361459, 2025). "However, Kinesin Family Member 4A (KIF4A), a member of the kinesin 4 subfamily of kinesin-related proteins, serves an important role in cell division, and its overexpression has been shown in cervical cancer." (PMID 41516135, 2025). "Genetically, KIF4A is upregulated due to amplification at Xq12106, and shows high expression in HPV16-positive cervical cancer, where it is enriched in pathways related to the cell cycle and DNA repair, potentially under the regulation of E2F." (PMID 41361459, 2025).
Intellectual disability (7 papers, 2015 to 2025). "It has been shown that mutations in KIF4A are related to seizures, autism and intellectual disability." (PMID 38339022, 2024). "Variants in KIF4A leading to exon-skipping and missense pathogenic variants have been reported in individuals with intellectual disability (ID)." (PMID 31616463, 2019). "Moreover, a functional deficiency in KIF4A is associated with intellectual disabilities, as mutations disrupt the balance of excitatory-inhibitory synaptic transmission, leading to neurodevelopmental delays and cognitive impairments." (PMID 41361459, 2025). "Diseases associated with KIF4A include mental retardation, X-linked 100, and retinoblastoma." (PMID 33959662, 2021). "KIF16B, KIF4A, and KIF5C mutations were found in clinical samples, and patients showed varying degrees of intellectual disability." (PMID 40964093, 2025). "Reducing KIF4A expression in primary rat hippocampal neurons disrupts the balance between excitatory and inhibitory synaptic transmission, providing a neurobiological explanation for the intellectual disabilities and epilepsy observed in affected individuals." (PMID 41361459, 2025).
oral squamous cell carcinoma (7 papers, 2013 to 2022). "Increasing KIF4A can promote the recruitment of macrophages toward oral squamous cell carcinoma cells and educate them to M2 polarized macrophages through regulating CCL2/CCR2." (PMID 33101367, 2020). "Considering the functions of KIF4A, we assumed that KIF4A is involved in progression of oral squamous cell carcinomas (OSCCs) via activation of the spindle assembly checkpoint (SAC)." (PMID 24386490, 2013).
esophageal squamous cell carcinoma (6 papers, 2021 to 2024). Esophageal squamous cell carcinoma (ESCC) is a type of esophageal carcinoma (EC) that can affect any part of the esophagus, but is usually located in the upper or middle third. "KIF4A knockdown can reduce esophageal squamous cell carcinoma cell proliferation, migration, and viability." (PMID 38937742, 2024). "In esophageal squamous cell carcinoma, KIF4A inhibits YAP1 phosphorylation, leading to enhanced nuclear YAP1 protein level." (PMID 37039264, 2023). "YAP1 induces KIF4A transcription by binding to the KIF4A promoter via TEA domain transcription factor 4 (TEAD4), contributing to the progression and poor prognosis of esophageal squamous cell carcinoma." (PMID 37039264, 2023).
endometrial cancer (5 papers, 2022 to 2025). Primary or metastatic malignant neoplasm involving the endometrium (mucous membrane that lines the endometrial cavity). "In endometrial cancer (EC), KIF4A expression is markedly increased and closely linked to poor prognosis." (PMID 41361459, 2025).
glioblastoma (5 papers, 2019 to 2025). The most malignant astrocytic tumor (WHO grade IV). "The subsequent multivariate Cox regression analysis results showed that KIF4A overexpression was a risk indicator for glioblastoma in both the TCGA and CGGA databases (TCGA: HR = 1.537, P < 0.001; CGGA: HR = 1.281, P < 0.001)." (PMID 38937742, 2024). "KIF4A promotes malignant progression of glioblastoma and transmission of TMZ resistance in the tumor microenvironment through the HIF1A/VEGFA axis." (PMID 41084153, 2025).
oral cancer (5 papers, 2013 to 2025). "According to the previous study on oral cancer, KIF4A depletion contributes to activating the SAC during cell division." (PMID 29396392, 2018). "Taken together, stratification of patients with OSCC based on KIF4A status may provide a more personalized approach to human oral cancer therapy." (PMID 24386490, 2013).
ovarian carcinoma (5 papers, 2021 to 2024). A malignant neoplasm originating from the surface ovarian epithelium. "BUB1 overexpression weakens KIF4A knockdown-mediated effects on cell viability, colony formation, migration, and apoptosis in ovarian cancer." (PMID 36787437, 2023). "The KIF4A oncogene silencing has been shown to inhibit cell proliferation and migration in ovarian cancer." (PMID 37371799, 2023). "As anticipated, we found that the down-regulation of of KIF4A expression after KPNA2 knockdown in ovarian cancer cell lines." (PMID 34034774, 2021). "The results of KIF4A analysis informed that KIF4A highly expressed in ovarian carcinoma tissues compared with normal ovarian tissues." (PMID 34034774, 2021). "Then, we identified the expression of KIF4A in ovarian carcinoma through GEPIA database and our own samples." (PMID 34034774, 2021). "By mining co-expression and correlation analysis data, we demonstrated that KPNA2 and KIF4A were both overexpressed in ovarian carcinoma." (PMID 34034774, 2021). "These experiments preliminarily validate that KPNA2 exerted its effects on the malignant behaviors of ovarian cancer cells through the KIF4A signaling pathway." (PMID 34034774, 2021). "Our results determined that KPNA2 is overexpressed in ovarian carcinoma and plays an important role in malignant transformation through regulating KIF4A signaling pathway." (PMID 34034774, 2021). "The results determined that KIF4A mRNA expression was significantly up-regulated in ovarian carcinoma samples compared with controls." (PMID 34034774, 2021). "Then, our own results further confirmed the overexpression of KIF4A mRNA and worse probabilities of survival in ovarian carcinoma." (PMID 34034774, 2021). "KPNA2, as a tumorigenic gene in ovarian cancer, accelerated tumor progression by up-regulating KIF4A, suggesting that KPNA2 might be a hopeful indicator of treatment and poor prognosis." (PMID 34034774, 2021). "Finally, the expression of KIF4A was inhibited by KPNA2 knockdown of KPNA2 in ovarian carcinoma cells." (PMID 34034774, 2021). "Also, we elucidate that KPNA2 has a role in malignancy mainly through the KIF4A signaling, which is a potential target for treating ovarian cancer." (PMID 34034774, 2021). "Above data elucidated that KPNA2 could promote ovarian carcinoma cell progression by up-regulating KIF4A in vitro." (PMID 34034774, 2021). "Moreover, we identified the expression level of KIF4A after KPNA2 knockdown in ovarian cancer cell lines." (PMID 34034774, 2021). "In addition, the expression of KIF4A may be influenced by the miR-29c-3p, the increased expression of which inhibits the proliferation and migration of cells in ovarian cancer." (PMID 37371799, 2023).
pancreatic cancer (5 papers, 2016 to 2025). "Further analysis using the public database GEPIA revealed that the expression of six genes (PLK1, SPC24, KIF2C, TOP2A, MKI67, and KIF4A) was significantly associated with overall survival in pancreatic cancer patients." (PMID 38250721, 2024). "Among these, PLK1, SPC24, KIF2C, TOP2A, MKI67, and KIF4A, have been implicated in cancer development and serve as important biomarkers of proliferative activity in pancreatic cancer." (PMID 38250721, 2024).
clear cell renal cell carcinoma (4 papers, 2022 to 2025). "In clear cell renal cell carcinoma (ccRCC), KIF4A is significantly overexpressed." (PMID 41361459, 2025).
colon carcinoma (4 papers, 2018 to 2023). "The expression of KIF4A in various types of cancer, including lung, breast, and colon cancer, has been found to be associated with poor prognosis in cancer patients." (PMID 38067227, 2023).
epilepsy (4 papers, 2021 to 2025). A brain disorder characterized by episodes of abnormally increased neuronal discharge resulting in transient episodes of sensory or motor neurological dysfunction, or psychic dysfunction. "In neuropsychiatric disorders, mutations in the KIF4A gene are closely linked to the pathogenesis of epilepsy." (PMID 41361459, 2025). "Germline variants in KIF4A have been linked to neurodevelopmental disorders, including X-linked intellectual disability and epilepsy, where impaired axonal transport and synaptic imbalance contribute to neurological phenotypes." (PMID 41361459, 2025). "KIF4A is involved in cell division and has been reported to underlie mild to moderate nonsyndromic ID, language delay, and epilepsy." (PMID 33982443, 2021). "Animal studies indicate that NAD supplementation can ameliorate the mutant phenotype, positioning KIF4A or PARP1 as potential intervention targets for epilepsy." (PMID 41361459, 2025).
esophageal cancer (4 papers, 2017 to 2025). A primary or metastatic malignant neoplasm involving the esophagus. "Decreased levels of COL4A1, DEK, GINS1, HPCAL1, KIF4A and RBMX predicted longer survival in esophageal cancer patients, while overexpression of IGFL1P1, LRRC57A-AS1, SNHG3, ULK3 and ZFYVE19 correlated with longer survival." (PMID 41326355, 2025). "The results showed that COL4A1, DEK, GINS1, HPCAL1, KIF4A and RBMX were significantly increased in esophageal cancer tissues and decreased in the combined treatment group, suggesting that are potential prognostic markers." (PMID 41326355, 2025). "KIF4A-based multi-gene signatures, such as KIF4A + RAD51AP1 + CDKN3 in oesophageal cancer, are poised to enter clinical practice as routine tools for molecular diagnostics and prognostic predictions, enabling more precise patient stratification." (PMID 41361459, 2025).
non-small cell lung carcinoma (3 papers, 2020 to 2025). A group of at least three distinct histological types of lung cancer, including non-small cell squamous cell carcinoma, adenocarcinoma, and large cell carcinoma. "Microarray data analyses revealed the highly transactivated status of KIF4A in non-small cell lung cancer and targeting KIF4A might hold a promise for the development of anticancer drugs and cancer vaccines as well as a prognostic biomarker in the clinic." (PMID 32322170, 2020).
breast tumor (2 papers, 2023). "There was a direct interaction between KIF4A and ERCC6L, and both are closely associated with mitosis and contribute to growth and metastasis of breast tumor." (PMID 37667329, 2023).
cholangiocarcinoma (2 papers, 2022 to 2025). A carcinoma that arises from the intrahepatic biliary tree (intrahepatic cholangiocarcinoma) or from the junction, or adjacent to the junction, of the right and left hepatic ducts (hilar cholangiocarcinoma). "It has been stated that the increased expression of KIF4A can affect the degree of immune cell infiltration, and it may be involved in the regulation of immune tolerance of cholangiocarcinoma cells." (PMID 35608059, 2022). "In cholangiocarcinoma (CCA), KIF4A is significantly upregulated, and its elevated expression correlates with poorer overall survival in patients." (PMID 41361459, 2025).
pancreatic ductal adenocarcinoma (2 papers, 2022 to 2025). An infiltrating adenocarcinoma that arises from the epithelial cells of the pancreas. "In contrast, an analysis of cBioPortal data revealed that KIF4A was upregulated in KRAS-mutant pancreatic ductal adenocarcinoma patient tissues." (PMID 36499051, 2022).
psoriasis (2 papers, 2025). An autoimmune condition characterized by red, well-delineated plaques with silvery scales that are usually on the extensor surfaces and scalp. "In psoriasis, the five diagnostic hub genes (KIF4A, DLGAP5, NCAPG, CCNB1, and CEP55) were predominantly expressed in keratinocytes, with significantly higher expression levels in patient samples compared to controls." (PMID 40406126, 2025). "Additionally, aspirin has been shown to inhibit ESCC progression by downregulating the ATAD2/KIF4A axis; while etoposide ameliorates psoriasis and Crohn’s comorbidity by regulating KIF4A." (PMID 41361459, 2025). "However, research on the role of KIF4A in psoriasis and CD remains relatively scarce." (PMID 40406126, 2025). "Additionally, KIF4A, KIF11, and KIF20A are linked to mitotic spindle formation and chromosome segregation, processes often disrupted in hyperproliferative conditions such as psoriasis and CD." (PMID 40406126, 2025). "In the psoriasis dataset (GSE13355), the AUC values for KIF4A (AUC = 0.99), DLGAP5 (AUC = 1), NCAPG (AUC = 0.99), CCNB1 (AUC = 0.99), and CEP55 (AUC = 0.99) exhibited exceptional diagnostic performance, with all values exceeding 0.7." (PMID 40406126, 2025). "This integrative approach highlighted KIF4A, DLGAP5, NCAPG, CCNB1, and CEP55 as key shared biomarkers for both psoriasis and CD." (PMID 40406126, 2025). "In the psoriasis validation cohort (GSE14905), the AUC values for KIF4A, DLGAP5, NCAPG, CCNB1, and CEP55 were 0.96, 0.97, 0.96, 0.98, and 0.93, respectively." (PMID 40406126, 2025). "Based on the existing findings, we hypothesize that KIF4A may regulate cell proliferation by maintaining mitosis, contributing to the abnormal proliferation of keratinocytes and intestinal epithelial cells in the pathogenesis of psoriasis and CD, thereby interfering with tissue repair processes." (PMID 40406126, 2025).
taurodontism (2 papers, 2019 to 2026). Taurodontism is a dental anomaly characterized by an elongated pulp chamber, displaced toward the apical floor of the tooth with no constriction at the level of the cemento-enamel junction, and short roots. "Here we report that missense variants in KIF4A (OMIM gene ID: 300521) cause an X-linked recessive triad of taurodontism, microdontia and dens invaginatus in two unrelated families." (PMID 31616463, 2019). "Since both pedigrees strongly imply that an X-linked basis for taurodontism, microdontia and dens invaginatus is a consistent triad phenotype, we further analyzed the segregation of the KIF4A and GLOD5 variants in other members of Family 1 from whom we had available DNA." (PMID 31616463, 2019).
urothelial bladder cancer (2 papers, 2023 to 2025). "Association of KIF4A expression with clinicopathological characteristics of patients with urothelial bladder carcinoma." (PMID 37039264, 2023). "In urothelial bladder cancer (UBC), KIF4A establishes a positive feedback loop with the Hippo pathway core molecule YAP1, collaboratively driving tumour progression." (PMID 41361459, 2025). "In urothelial bladder cancer (UBC), YAP1 promotes KIF4A transcription, while KIF4A inhibits YAP1 phosphorylation, facilitating its nuclear translocation and activation, thus creating a self-amplifying oncogenic circuit." (PMID 41361459, 2025).
astrocytoma (1 paper, 2019). "In addition, the mRNA expression of KIF4A, 9, 18A, and 23 was significantly increased in astrocytoma compared with that in oligoastrocytoma and oligodendroglioma." (PMID 30872592, 2019). "Additionally, we observed that the mRNA levels of KIF4A, KIF9, KIF18A, and KIF23 were elevated in LGG patients with a higher histological grade and astrocytoma histologic type than in those with a lower histological grade and histologic type, including oligoastrocytoma and oligodendroglioma." (PMID 30872592, 2019).
autoimmune disease (1 paper, 2025). A disorder resulting from loss of function or tissue destruction of an organ or multiple organs, arising from humoral or cellular immune responses of the individual to their own tissue constituents. "Additional evidence implicates KIF4A in viral entry (HBV/HDV), autoimmune disease, fibrosis, and congenital anomalies, emphasizing that its dysregulation affects diverse physiological systems." (PMID 41361459, 2025).